ABCF2-H2BK1 (ABCF2-H2BK1 readthrough)
Synonyms: ABCF2-H2BE1
Gene: Protein-coding gene on chromosome 7 (151,207,837 to 151,227,166, reverse strand). Ensembl gene ENSG00000285292.
Genetic constraint (gnomAD): Loss-of-function variants: 38 observed, 78.65 expected, observed/expected ratio (o/e) 0.48, 90% interval 0.37 to 0.63. The upper end of that interval is the gene's LOEUF score, 0.63, which puts it in group 2 of 6, group 1 being the genes least tolerant of losing a copy. Missense variants: 525 observed, 814.34 expected, observed/expected ratio (o/e) 0.64, 90% interval 0.6 to 0.69. Synonymous variants: 300 observed, 300.48 expected, observed/expected ratio (o/e) 1, 90% interval 0.91 to 1.1.